PTH (parathyroid hormone)
Diseases named in the same sentence as PTH in open-access papers (continued):
Sharing a sentence is not in itself a finding about the gene and the disease.
osteoporosis (continued). "The clinical use of PTH, such as teriparatide, in a dose of 20 μg daily has been shown to decrease the risk of vertebral fractures by 65% and nonvertebral fractures by 53% in patients with osteoporosis after an average of 18 months of therapy." (PMID 31064048, 2019). "In addition to the effect of PTH in pHPT, low BMD may also be caused by such other factors as primary osteoporosis, especially in postmenopausal women." (PMID 31451913, 2019). "However, further studies of our team are being perform, aiming to show not only the local effect of osteoporosis drugs (raloxifene, strontium ranelate, PTH), but the systemic effect of these drugs and whether they show any adverse effect." (PMID 29742257, 2018). "Several agents have been used for the treatment of osteoporosis, including: bisphosphonates (alendronate, ibandronate, risedronate, and zoledronic acid), calcitonin, selective estrogen receptor modulators (raloxifene), parathyroid hormone (teriparatide), and RANK-ligand inhibitors (denosumab)." (PMID 28793342, 2017). "In addition, intermittent PTH can effectively treat osteoporosis of the hip and spine." (PMID 28438150, 2017). "We did not measure serum markers which may be possible mechanisms for the link between coronary CAC, osteoporosis, and bone fragility, such as bone resorption, estrogen, vitamin D, parathyroid hormone, calcium intake, thyroid-stimulating hormone, T3, free T4, or osteoprotegerin levels." (PMID 29422704, 2017). "However, it still remains unclear which BM stromal cells give rise to osteoblasts in response to PTH treatments, thereby mediating the therapeutic response in osteoporosis." (PMID 28694469, 2017). "Consequently, osthole may share the similar potential as PTH on preventing fragility fracture and enhancing healing of fractures when normal process fails in patients with osteoporosis and can be applied in prolonged therapy as BPs to restore BMD." (PMID 27538772, 2016). "Many drugs including bisphosphonates, PTH/teriparatide, and denosumab are used very successfully in the clinic to augment bone mass and prevent fracture in osteoporosis, but it remains somewhat controversial whether any has clinical benefit in fracture healing." (PMID 26573091, 2016). "Our findings showed that low serum Mg levels may impact PTH levels and deteriorate osteoporosis." (PMID 26273297, 2015). "Therefore, we designed this meta-analysis of all available randomized controlled trials (RCTs) to quantitatively investigate whether combination therapy is superior to PTH analogues alone for the treatment of osteoporosis." (PMID 26402797, 2015). "Notably, other new drugs such as recombinant human parathyroid hormone (rhPTH) may prove useful in the treatment of primary osteoporosis." (PMID 24906390, 2014). "The higher plasma PTH in African-Americans, however, may not lead to a similarly increased rate of bone turnover or risk of osteoporosis as it does for White-Americans." (PMID 24621477, 2014). "Furthermore, the OVX mouse provides a model that may be more relevant to the clinical applications of PTH in the treatment of osteoporosis." (PMID 19851510, 2009). "The effects of parathyroid hormone (PTH) on bone metabolism are well established and the presence of osteoporosis is the main reason for surgical intervention with parathyroidectomy, ultimately to prevent fractures." (PMID 40690900, 2026). "Additionally, the constraints of the available databases limited the capacity to control for all potential confounding variables, such as comorbid conditions like osteoporosis and fluctuations in parathyroid hormone levels, both of which may influence vitamin D levels and auditory health." (PMID 40388403, 2025). "The parathyroid hormone (PTH) is commercially available and used to increase bone mass and reduce fractures in patients with osteoporosis." (PMID 41476619, 2025).
osteoporosis (continued). "Currently, most osteoporosis therapies target osteoclasts to inhibit bone resorption, while the three FDA-approved anabolic agents include parathyroid hormone, parathyroid hormone-related protein, and anti-sclerostin antibody that promote osteoblast function." (PMID 41369394, 2025). "Established therapies of parathyroid hormone (PTH) analogs effectively promote bone formation and reduce fractures in severe osteoporosis, but their use is limited by potential adverse effects." (PMID 40153305, 2025). "Multivariate regression analysis identified menopause duration, PTH, ALP, and estrogen levels as independent predictors of osteoporosis in women with diabetes, while BMI emerged as a protective factor." (PMID 40428747, 2025). "In our study, patients with osteoporosis had lower Ca, P, and vitamin 25 OH D levels but higher ALP and PTH levels." (PMID 40095502, 2025). "It contains fragment 1–34 of the human parathyroid hormone (PTH), which is also the API of teriparatide (ForteoTM), a drug approved by the FDA in 2002 for the treatment of osteoporosis." (PMID 39942587, 2025). "PTH and CD59 were significantly upregulated in all kinds of parathyroid subpopulation in osteoporosis patients." (PMID 40496565, 2025). "Studies have reported that venom extracts from certain scorpions can restore serum levels of serum ALP, TRAP, PTH, osteocalcin, TNF-α, and bone minerals in OVX rats, combatting osteoporosis and enhancing BMD." (PMID 41208866, 2025). "In addition, anthropometric parameters (weight, BMI), densitometric parameters (BMD, T-score), and biochemical markers (vitamin 25(OH)D total, PTH) may be useful markers in personalized medicine for screening postmenopausal osteoporosis and may serve as predictive biomarkers of osteoporosis." (PMID 40149488, 2025). "Different pathways interaction analysis revealed that osteoporosis patients had higher levels of NOTCH, PTH, FGF, and EGF pathway whereas non-osteoporosis patients had highest level of NRG pathway." (PMID 40496565, 2025). "GO and KEGG enrichment revealed PTH, NOTCH, FGF, EGF and CD59 pathways were significantly up-regulated in all parathyroid subpopulations in osteoporosis patients." (PMID 40496565, 2025). "Parathyroid hormone (PTH) is a key regulator of bone homeostasis and along with its analogs has been used to treat osteoporosis." (PMID 40609791, 2025). "We present a case of a 71-year-old female patient who exhibited gradual increases in both serum calcium and parathyroid hormone (PTH) levels, along with the development of osteoporosis, suggesting the presence of PHPT." (PMID 40709121, 2025). "Teriparatide, a recombinant form of the first 34 amino acids of human parathyroid hormone (rhPTH1-34; hereafter PTH), is a bone anabolic drug used to treat severe osteoporosis, characterized by low bone mineral density and an increased fracture risk." (PMID 38661167, 2024). "Osteoporosis treatments aim to preserve BMD and prevent fractures, utilizing therapies such as bisphosphonates, denosumab, and PTH analogs." (PMID 38334917, 2024). "Intermittent administration of parathyroid hormone (PTH), an anabolic agent approved for the treatment of osteoporosis, was found to increase the expression of IGFBP7 in mouse MSCs and pre-osteoblasts." (PMID 39045455, 2024). "Subsequent studies have focused more on studying the effects of PTH on bone structure and bone density after SCI, as well as research related to osteoporosis and fracture healing involving PTH replacement therapies such as teriparatide." (PMID 38711562, 2024). "Ligustroflavone, an active compound in Ligustrum lucidum (Scrophulariaceae), has been found elevate parathyroid hormone (PTH) levels in diabetic mice, regulate calcium metabolism, and prevent osteoporosis." (PMID 38510656, 2024). "Teriparatide, human parathyroid hormone (PTH) 1–34, is an anabolic drug for osteoporosis, known to prevent the occurrence of new vertebral fractures and counteract LBP." (PMID 37238956, 2023).
osteoporosis (continued). "Hyperparathyroidism is characterized by the abnormal circulating levels of parathyroid hormone (PTH) and calcium that can lead to osteoporosis, renal calculi, and cognitive deficits." (PMID 38239660, 2023). "Hence, it was hypothesized that gastrin and PTH played a key role in osteoporosis because adding octreotide to correct hypergastrinemia in the rats consuming pantoprazole caused no significant changes in the number of osteoclasts and osteoblasts compared to the controls." (PMID 37711876, 2023). "Age, years since menopause, and circulating IL-6, PTH, and IGFBP-3 were significantly higher in the osteoporosis group compared to the normal group." (PMID 37035758, 2023). "Compared to the normal women, age, years duration of menopause, and circulating IL-6, PTH, and IGFBP-3 were significantly higher in the osteoporosis women." (PMID 37035758, 2023). "The level of serum albumin was lower (p = 0.002), and the levels of bone metabolism markers, including intact PTH (p < 0.001), sALP (p < 0.001), ß-CTX (p = 0.01), and P1NP (p < 0.001), were significantly higher in osteoporosis patients." (PMID 37093441, 2023). "Therefore, the low level of PTH may also contribute to the patient’s osteoporosis." (PMID 37907913, 2023). "PTH analogs, such as PTH1-34, are considered to be the most effective and currently FDA-approved anabolic therapy for patients with osteoporosis." (PMID 36918976, 2023). "More studies are needed to better understand the PTH or abaloparatide/PTHR1 pathway and to develop better anabolic treatments for osteoporosis." (PMID 36751417, 2023). "Parathyroid hormone (PTH) and calcitonin are also approved for the treatment of osteoporosis and have been shown to increase bone density and reduce fracture risk." (PMID 37680888, 2023). "Because microRNA-mediated silencing of IGFBP5 has been shown to promote osteoporosis, it is possible that attenuated expression of this gene in parathyroid adenomas could contribute to bone mineral density loss in PHPT in addition to the direct osteoclastic effects of PTH." (PMID 36992820, 2023). "Obtained results demonstrate that a combination of single-dose local administration of PTH and β-TCP/Col had an additive effect on local bone formation in osteoporosis rats." (PMID 36984115, 2023). "In this study, we have explored the effect of single or combined administration with PTH and ZOL on implant loosening in a rat model of osteoporosis." (PMID 35546997, 2022). "In our study, it was also found that patients with rotator cuff injuries with osteoporosis experience changes in OCN and PTH levels." (PMID 36465653, 2022). "PTH was reported to promote bone remodeling, and teriparatide (PTH1-34) was approved by FDA as an anabolic therapy for clinical treatment of osteoporosis." (PMID 34978631, 2022). "Parathyroid hormone (PTH) is a crucial regulator of bone development, and patients with hyperparathyroidism are more likely to develop osteoporosis." (PMID 35909545, 2022). "Bone regenerative therapeutics such as PTH (1–34, Forteo®), are FDA approved treatments for osteoporosis, and have vast potential to reverse microgravity-induced bone loss." (PMID 36172011, 2022). "In summary, PTH is involved in many clinical situations, such as osteoporosis, CKD-BMD, and ectopic calcification; thus, the precise detection and quantification of PTH in the blood would be of great value in this regard." (PMID 36293083, 2022). "Parathyroid hormone (PTH), the only FDA-approved anabolic treatment for osteoporosis, is important in calcium-phosphate homeostasis." (PMID 36060945, 2022). "It has been suggested that the anabolic effect of the parathyroid hormone (PTH), an FDA approved osteo-anabolic drug commonly used for osteoporosis treatment, requires Sfrp1 downregulation to stimulate Wnt signaling and osteoblastogenesis." (PMID 34452242, 2021).
osteoporosis (continued). "Parathyroid hormone (PTH) was the first-ever drug to be approved by the Food and Drug Administration (FDA) in the U.S. for the remedy for osteoporosis." (PMID 33925324, 2021). "Pharmacological targeting of osteoblasts or the balance between osteoblasts and osteoclasts is already an accepted strategy for the treatment of osteoporosis, and the FDA-approved osteoporosis drugs target RANKL, parathyroid hormone, and sclerostin." (PMID 34073480, 2021). "Parathyroid hormone (PTH), a U.S. Food and Drug Administration–approved anabolic agent for osteoporosis, regulates bone remodeling and calcium metabolism." (PMID 33646122, 2021). "While PTH (Teriparatide) and SOSTi (Romosozumab) are FDA-approved for use in patients with osteoporosis, both drugs have risks." (PMID 34140410, 2021). "Our study could not show a causal relationship between PM10 and osteoporosis because we were not able to access individuals’ serum vitamin D or parathyroid hormone levels in the claims data; however, based on the results from previous studies, we hypothesize underlying mechanisms." (PMID 34610796, 2021). "Multiple analogs of parathyroid hormone, all of which bind to the PTH/PTHrP receptor PTH1R, are used for patients with osteoporosis and hypoparathyroidism." (PMID 33977197, 2021). "Persistent levels of increased parathyroid hormone (PTH) result in a higher incidence of osteopenia and osteoporosis compared to the general population." (PMID 34440663, 2021). "Generally speaking, our study found significant difference in the creatinine, eGFR, PTH, β-CTX and 25(OH)D levels between the osteoporosis and control groups." (PMID 33315972, 2020). "Parathyroid hormone (PTH) is an anabolic bone drug approved by the US Food and Drug Administration (FDA) to treat osteoporosis." (PMID 31291372, 2019). "Teriparatide, a parathyroid hormone (PTH) analogue, is a synthetic polypeptide hormone consisting of the 1–34 fragment of PTH, which is used in treatment of osteoporosis." (PMID 30953554, 2019). "Intermittent administration of a fragment of Parathyroid hormone (PTH) activates osteoblast-mediated bone formation and is used in patients with severe osteoporosis." (PMID 30902975, 2019). "Studies that were done on current treatments of osteoporosis such at BMP2 and PTH showed that long-term usage of these compounds resulted in enhancing osteoclast differentiation and bone resorption." (PMID 30294717, 2018). "Other than those well-known markers, Parathyroid Hormone (PTH) is known as the regulator of serum calcium and phosphate metabolism in bone and can act as an osteoporosis-related biomarker in parathyroid disorders." (PMID 30181433, 2018). "Systemic subcutaneous injections of PTH, and its derivative human recombinant PTH (hrPTH 1-34), are FDA-approved for the treatment of osteoporosis, and have been used as effective off-label treatments of fracture healing." (PMID 30096765, 2018). "The level of H2S in the plasma was determined and common laboratory indicators to diagnose osteoporosis, such as alkaline phosphatase (ALP) activity and the levels of osteocalcin (OCN), calcitonin, parathyroid hormone and leptin were measured." (PMID 30305826, 2018). "While there is a diverse armamentarium to serve as inhibitors of the osteoclastic activity, PTH was the first anabolic agent approved by the FDA (Food and Drug Administration (USA)) for the treatment of osteoporosis in 2002." (PMID 30366476, 2018). "Mean PTH was 4.8 and 4.3 pmol/L (p = 0.08) and mean 25(OH) vitamin D3 concentrations were 56.1 and 54.8 nmol/L (p = 0.81) for the normal BMD and osteoporosis groups, respectively." (PMID 29789485, 2018). "Daily treatment with alendronate immediately after the discontinuation of PTH maintains or increases BMD of the lumbar spine and femoral neck in postmenopausal women with osteoporosis." (PMID 28246925, 2017).
osteoporosis (continued). "Therefore, intermittent PTH administration can be effective in improving the bone density at the implant placement site and achieving favorable primary stability and osseointegration in patients with severe osteoporosis, including that induced by glucocorticoids." (PMID 29069147, 2017). "PTH is also relatively safe and is superior to other FDA‐approved therapies for osteoporosis (e.g., antiresorptive agents) in improving bone density and quality, and reducing fracture risk." (PMID 28963125, 2017). "The apparent protective effect of obesity on osteoporosis based on the effect of obesity on BMD masks the effect of obesity on vitamin D, PTH, and obesity-induced insulin resistance." (PMID 28124221, 2017). "Both cortical and trabecular bones are typically decreased in osteoporosis; however, the mineral bone disease in CKD patients with high PTH levels predominantly decreases the cortical bone, but increases the trabecular bone." (PMID 27855207, 2016). "Previous studies have demonstrated ovariectomy in animals to lead to osteoporosis and decreased BMD, and Teriparatide (PTH) administration to improve BMD and strength of bone." (PMID 26466092, 2015). "Teriparatide, a recombinant human parathyroid hormone (PTH), is currently the only FDA approved anabolic agent in the United States for the treatment of osteoporosis." (PMID 25202461, 2014). "Human parathyroid hormone (PTH), used clinically to treat osteoporosis, was used as a model to verify our method." (PMID 22442680, 2012). "Intermittent administration of parathyroid hormone (PTH) has an anabolic effect on bone, as confirmed in human osteoporosis studies, distraction osteogenesis, and fracture healing." (PMID 22880714, 2012). "Bisphosphonates and parathyroid hormone (PTH) represent the antiresorptive and anabolic classes of drugs for osteoporosis treatment." (PMID 22022584, 2011). "These factors limit the ability to elucidate the age-, ethnic- and gender- specific effects of PTH and bisphosphonates on BMD in osteoporosis treatment." (PMID 22022584, 2011). "Given that injections of PTH is approved for the treatment of osteoporosis, it has been suggested that short acting calcilytics, causing bursts of PTH levels similar to the injected PTH rather than the sustained increases seen with NPS 2143, could lead to increases in BMD." (PMID 19305800, 2007). "Because the patient’s osteoporosis management was initially conducted in the rheumatology department of another hospital, laboratory data such as PTH, vitamin D, and bone resorption markers were not available and were self-reported by the patient." (PMID 41560080, 2026). "Therefore, therapeutic strategies targeting senescent cells in conjunction with PTH treatment may represent a promising approach to enhance the efficacy and sustainability of PTH therapy, particularly in older individuals who account for the majority of patients with osteoporosis." (PMID 41432314, 2026). "What’s more, the serum concentration of TRAP, calcium (CA), and phosphate (P) also increased in CUMS mice, while parathyroid hormone (PTH) level in serum decreased, which indicated that they might be in the initial phase of osteoporosis." (PMID 39773351, 2025). "Secondly, certain information related to osteoporosis progression, such as sex hormone levels and PTH, was not accessible or absent from the NHANES database." (PMID 39913394, 2025). "Routine measurement of serum calcium or i-PTH is not performed in asymptomatic patients without osteoporosis; in this group, therefore, the diagnosis of PTHT is not made at such an early stage." (PMID 41156271, 2025). "Generally, patients diagnosed with PHPT frequently present with osteoporosis and/or urolithiasis due to the complications of long-term high PTH (with or without elevated serum ionized calcium)." (PMID 39518465, 2024).